INS (insulin)
Diseases named in the same sentence as INS in open-access papers (continued):
Sharing a sentence is not in itself a finding about the gene and the disease.
Insulin resistance (continued). "These include inflammatory markers (such as C-reactive protein), metabolic syndrome indicators, vitamin D and insulin resistance indicators (such as the insulin resistance index and insulin sensitivity index), which are believed to be potentially associated with the risk of prediabetes." (PMID 39883666, 2025). "Additionally, a 2018 case report highlighted the improvement in blood glucose control in a DM1 patient with severe insulin resistance and hyperinsulinemia after using insulin sensitizers, including pioglitazone." (PMID 41018201, 2025). "Most patients with T2DM have insulin resistance and insulin secretion dysfunction, where the increased demand for insulin action caused by resistance is not compensated by insulin secretion." (PMID 39147370, 2025). "Additionally, the polyphenolic small molecule Resveratrol can restore insulin sensitivity in skeletal muscle cells, augment glucose uptake, reverse insulin resistance, and improve GLUT4 translocation." (PMID 41373699, 2025). "The downregulation of MPC in obesity may contribute to insulin resistance by promoting a metabolic shift toward increased fatty acid oxidation and the accumulation of lipid intermediates that interfere with insulin signaling pathways." (PMID 40001526, 2025). "GQD lowers blood glucose levels by improving insulin resistance and enhancing insulin sensitivity." (PMID 41552833, 2025). "Enhancing central insulin signaling, especially in individuals with insulin resistance, may further normalize dopaminergic function and contribute to the reversal of anhedonic phenotypes." (PMID 41010364, 2025). "Despite the well-established research on the association between skeletal health and circulating insulin level, insulin resistance, and insulin therapy, the underlying signalling pathways mediating insulin’s action in bone cells are not well defined." (PMID 40564223, 2025). "This condition results from disruption in glucose metabolism, often stemming from insufficient insulin production by the pancreas, reduced in insulin effectiveness in body tissues (insulin resistance), or a combination of these factors, which is particularly common among older adults." (PMID 40390089, 2025). "This might be explained by the physiological cardiovascular effects of insulin and the role of insulin resistance in hypertension and atherosclerosis." (PMID 40004196, 2025). "In participants with IR, WC, HC, WHR, plasma glucose, plasma insulin, and the homeostatic model assessment for insulin resistance (HOMA-IR) were significantly higher (P < 0.05 all), with trends toward increases in BW (P = 0.058) and BMI (P = 0.052) compared to participants without IR." (PMID 41271970, 2025). "Furthermore, GGE03 improved serum metabolic markers, including glucose, triglycerides, total cholesterol, and insulin levels, while also reducing insulin resistance." (PMID 41009518, 2025). "While insulin resistance appears to play a role, additional factors—such as altered hepatic insulin signaling, glucagon dominance, adipose tissue dysfunction, and autoimmune inflammation—may contribute in this setting." (PMID 40807122, 2025). "The higher depression behavior in APP/IR‐dKI mice may be induced by insulin resistance, especially in the brain, and the lower anxiety behavior may be elicited by peripheral insulin resistance." (PMID 40443027, 2025). "Leptin has been reported to block insulin secretion in pancreatic β-cells, whereas leptin resistance was found to provoke the continuous secretion of insulin, which may promote insulin resistance." (PMID 40095937, 2025). "GDM arises when insulin resistance cannot be compensated by maternal insulin secretion." (PMID 40362828, 2025). "Both obesity and nonobesity groups showed significant improvements from baseline to endline in weight, BMI, glycemic markers (HbA1c and FBG), fasting insulin, insulin resistance indices (HOMA-IR and QUICKI), blood pressure, and lipid parameters (triglycerides, non-HDL, and HDL-C)." (PMID 40843316, 2025).
Insulin resistance (continued). "Obesity is a significant contributor to insulin resistance; the excessive accumulation of adipose tissue induces adipocyte hypertrophy, which releases factors such as free fatty acids (FFAs) that disrupt insulin signaling pathways and reduce cellular sensitivity to insulin." (PMID 40136413, 2025). "Insulin resistance is a condition of impaired tissue reactivity to insulin." (PMID 41009549, 2025). "In recent years, continuous intraperitoneal insulin infusion (CIPII) has become a valid therapeutic option to achieve good glycemic control for patients with unstable type 1 diabetes and subcutaneous insulin resistance, mainly due to the absorption of insulin through the portal venous system." (PMID 40995084, 2025). "While insulin secretion defects are the primary mechanism in CFRD pathophysiology, insulin resistance may act as an additional risk factor that accelerates CFRD development." (PMID 41300682, 2025). "Accumulating evidence from experimental and clinical studies suggests that GDM is essentially a state of chronic insulin resistance, largely mediated by proinflammatory cytokines that impair insulin signaling and reduce insulin secretion from pancreatic β-cells." (PMID 41210501, 2025). "Interestingly, in GDM pregnancies, although the maternal peripheral tissues develop insulin resistance, the placenta remains insulin responsive." (PMID 40497429, 2025). "In the C200 group, both serum insulin and leptin levels were significantly reduced compared with those of the Veh group, suggesting that the improvement in insulin resistance by CJE may be from the regulation of energy balance." (PMID 39815341, 2025). "Additionally, F344 rats display genetic insulin resistance from an early age, while maintaining regular levels of glucose, requiring significant higher insulin levels to regulate blood glucose." (PMID 40493338, 2025). "The improvement of insulin resistance (IR) and its detrimental effects on the brain, along with enhanced insulin signaling by DGF, confirmed our initial hypothesis that DGF improves cognitive function and enhances learning and memory in treated rats." (PMID 40397120, 2025). "In addition, during oral glucose tolerance testing, pharmacologic interventions, and acute exercise testing, these TAGs increased in response to insulin action and were poorly correlated with insulin resistance." (PMID 39544124, 2025). "Insulin resistance occurs when tissues become unresponsive to normal insulin levels." (PMID 40564199, 2025). "Following initial findings suggesting altered insulin sensitivity in migraine patients, several studies have explored the relationship between insulin resistance (IR), metabolic syndrome (MetS), and migraine, including the potential for targeted therapeutic interventions." (PMID 40426647, 2025). "In addition, the increase of inflammatory factors and stress hormones can also interfere with the insulin signaling pathway, further aggravating the degree of insulin resistance." (PMID 40475963, 2025). "The identification of PTP1B and PP2A as key players in insulin resistance induced by EVs may have potential therapeutic relevance for the maintenance of insulin signalling in individuals with insulin resistance." (PMID 39422717, 2025). "Conversely, in T2DM, insulin resistance or oxidative stress contributes to BM dysfunction by impairing insulin signaling in podocytes, resulting in structural damage, proteinuria, and glomerulosclerosis, which exacerbates DN and the progression of chronic kidney disease." (PMID 40002316, 2025). "In addition, hydrolysis products of elevated triglycerides, such as free fatty acids, can induce insulin resistance by inhibiting insulin signal transduction and reducing the number of insulin receptors on target cells." (PMID 40512995, 2025). "By optimizing their metabolic profiles, this dietary intervention may enhance insulin sensitivity and mitigate insulin resistance in patients with MetS." (PMID 41458553, 2025).
Insulin resistance (continued). "Additionally, high blood triglyceride levels can increase ceramide and nitric oxide, suppressing muscle insulin activity and disrupting glucose uptake, ultimately leading to beta-cell death and insulin resistance." (PMID 40589514, 2025). "Chronic periodontal diseases can further exacerbate insulin resistance and impair glycemic control, whereas periodontal treatment that reduces inflammation may improve insulin sensitivity." (PMID 40418274, 2025). "Moreover, due to the retrospective nature of the data, we were unable to include direct measures of insulin resistance such as fasting insulin or HOMA-IR." (PMID 40686695, 2025). "However, persistent HFD promotes insulin resistance, resulting in increased insulin secretion, but insulin becomes unable to perform its normal function." (PMID 40431382, 2025). "HFD/STZ significantly affected glucose homeostasis, as demonstrated by increased fasting blood glucose levels, serum insulin levels, homeostasis model assessment of insulin resistance (HOMA‐IR) index, and impaired oral glucose tolerance test (OGTT) and insulin tolerance test (ITT)." (PMID 39741391, 2025). "Notably, mitochondrial fragmentation alone can impair insulin-stimulated Akt activity and glucose uptake in myocytes, underscoring its contribution to redox-driven insulin resistance." (PMID 41226411, 2025). "HOMA-IR, while clinically convenient, is an indirect measure of insulin resistance; more precise methods, such as hyperinsulinemic-euglycemic clamps, could provide deeper insights into the mechanistic link between insulin action and GH responsiveness." (PMID 41282298, 2025). "These compounds may improve metabolic syndrome by increasing adiponectin, decreasing leptin, reducing insulin resistance, elevating insulin levels, and blocking calcium channels." (PMID 41427055, 2025). "Furthermore, triglyceride-induced hepatic insulin resistance diminishes insulin’s inhibitory effect on gluconeogenesis, further amplifying glucose production." (PMID 41155203, 2025). "The increased insulin concentration observed in children born SGA may reflect either decreased insulin sensitivity or increased insulin resistance and it may progress to metabolic syndrome later in life." (PMID 40889096, 2025). "Hypomethylation is typically associated with increased gene expression, suggesting that the elevated Fndc5 expression may lead to dysregulation of insulin sensitivity pathways and contribute to insulin resistance." (PMID 41509541, 2025). "Insulin resistance develops by deteriorating glucose homeostasis in mice treated with resistin, and administration of resistin antibodies in mice with dietary obesity reduces blood glucose levels and increases insulin sensitivity." (PMID 41417360, 2025). "Notably, NMN administration improved whole‐body glucose intolerance and insulin resistance and decreased insulin concentrations during IPGTTs in VeNKO mice." (PMID 41021357, 2025). "Numerous hormones regulate maternal insulin resistance and insulin secretion during pregnancy." (PMID 40944254, 2025). "In contrast, skeletal muscle glycogen levels were significantly lower in the prediabetic group compared to the non-prediabetic group, likely reflecting impaired insulin-mediated glucose uptake associated with insulin resistance." (PMID 39861423, 2025). "Based on previous studies demonstrating how NLRP3 inhibition ameliorates insulin-resistance, Liang and colleagues demonstrated that fasting improves insulin sensitivity in mice and reverses insulin resistance in vitro, specifically in adipocytes used as a cellular model of insulin resistance." (PMID 39899119, 2025). "Insulin resistance (IR) is a clinical state of decreased insulin sensitivity and responsiveness." (PMID 40810068, 2025). "In addition, early-stage AD has been found to be associated with high insulin concentrations in response to glucose challenge (hyperinsulinaemia) in combination with reduced insulin-mediated glucose uptake (insulin resistance)." (PMID 40607038, 2025).
Insulin resistance (continued). "Another hypothesized metformin mechanism is its insulin-sensitizing properties, as insulin resistance may play a role in some cases of melasma." (PMID 41149049, 2025). "Cinnamon can significantly reduce fasting insulin and insulin resistance in women with PCOS." (PMID 40842497, 2025). "Treatment of the diabetic rats with linagliptin led to a significant increase in both insulin and C-peptide secretion when compared with the diabetic animals which suffer from insulin resistance as well as damage to β-cells in the islets of Langerhans due to the effect of NA/STZ injection." (PMID 40430475, 2025). "Obesity-related insulin resistance may lead to higher insulin requirements and further challenges around glucose management." (PMID 40553147, 2025). "However, replacing HOMA2-B and HOMA2-S with the Stumvoll and Matsuda indices also identified women who had comparable insulin resistance and insulin secretion to the NGT population." (PMID 39621104, 2025). "Emerging evidence suggests that AD may involve a brain-specific form of insulin resistance, wherein insulin signaling becomes impaired in key regions responsible for memory and cognition." (PMID 40787193, 2025). "In addition, impairment of several insulin/IGF signaling pathway genes—relevant to insulin resistance and compromised glucose metabolism—was attributed to increased interferon regulatory factor 1 (IRF1) expression and its observed activity or effect." (PMID 41488148, 2025). "Additionally, LASSBio-2129 improved insulin sensitivity in the dexamethasone-induced insulin resistance model, with effects comparable to sitagliptin." (PMID 41155701, 2025). "However, these inflammatory pathways simultaneously impair insulin signaling, which promotes insulin resistance." (PMID 40282189, 2025). "In obesity and insulin resistance, elevated basal insulin concentrations and blunted catecholamine responses suppress adipose tissue lipolysis and reduce plasma free fatty acid availability, while mitochondrial dysfunction and altered substrate delivery further constrain oxidation capacity." (PMID 41590220, 2025). "Altogether, current evidence supports the idea that the primary cause of insulin resistance is not defects in proximal insulin signaling." (PMID 40806697, 2025). "Interestingly, the phenotype of our mice injected with shOlfr734 is characterized by an increase in insulin secretion, suggesting potential insulin resistance." (PMID 40806011, 2025). "In the sarcopenic environment, clinicians should be aware of circulus vitiosus of insensitivity to insulin and adipokines profile deterioration, with possible positive outcomes achieved through lifestyle or therapeutic interventions to minimize insulin resistance." (PMID 40075777, 2025). "Obesity induces adipocyte senescence followed by a senescence-associated secretory phenotype (SASP) like decreased adiponectin secretion, which triggers a cascade of reactions leading to inflammation, insulin signaling disruption, insulin resistance, and severe metabolic disorders." (PMID 40308696, 2025). "Taken together, defects in insulin signaling and systemic insulin resistance may play significant roles in the pathogenesis of AD." (PMID 39966707, 2025). "However, in obesity, chronic activation of mTORC2 disrupts insulin signaling, contributing to insulin resistance and metabolic inflexibility." (PMID 40218884, 2025). "Generally, GLP-1 supports glucose metabolism by promoting insulin sensitivity, however, chronically high GLP-1 levels can contribute to insulin resistance through GLP-1 receptor desensitisation and cause reduced blood insulin secretion and increased blood glucose, as observed in these animals." (PMID 40524248, 2025). "This study aimed to evaluate the effect of Momordica charantia on fasting blood glucose (FBG), glycated haemoglobin (HbA1c), insulin, homeostatic model of insulin resistance (HOMA-IR), and homeostatic model of β-cell function (HOMA-β) in individuals with prediabetes or T2D." (PMID 41280283, 2025).
Insulin resistance (continued). "Its overexpression impairs insulin signaling and promotes insulin resistance." (PMID 40299563, 2025). "IFNγ induced metabolic pathways, such as nitric oxide (NO) production and tryptophan catabolism, which can interfere with mitochondrial function, insulin sensitivity, and lipid metabolism, exacerbating conditions like insulin resistance, obesity-related inflammation, and autoimmunity." (PMID 40453076, 2025). "During the early stages of insulin resistance, elevated insulin secretion may temporarily compensate to maintain metabolic balance, potentially masking its relationship with MetS." (PMID 39941416, 2025). "Given the potential biological link between insulin resistance and tumor progression, it is worth investigating the feasibility of adding insulin sensitizers (such as metformin) or adjusting the intensity of adjuvant chemotherapy for high-risk patients on top of standard treatment." (PMID 41019567, 2025). "To clarify the causality relationship between cytokines IL-1α, IL-1β and IL-6 from macrophages and insulin resistance, we co-cultured primary hepatocytes with BMDMs and treated them with different combinations of insulin, TSH, IL-1 blocker IL-1RA or IL-6 blocker IL-6ST." (PMID 40523992, 2025). "Lean NAFLD patients often exhibit insulin resistance and dyslipidemia, and these metabolic abnormalities may promote colorectal carcinogenesis through activation of the insulin–IGF signaling pathway." (PMID 41514634, 2025). "There were no significant longitudinal associations of baseline serum insulin and insulin resistance markers with changes in cognition over time." (PMID 40478656, 2025). "Insulin dose reduction is often assumed to imply a reduction in insulin resistance." (PMID 41285865, 2025). "Estrogen replacement in postmenopausal women has been associated with a reduction in circulating NEFA during hyperinsulinemia, but the precise impact of HRT on adipose tissue insulin sensitivity has yet to be defined using gold-standard measurements of adipose tissue insulin resistance." (PMID 40522859, 2025). "It is generally believed that the primary cause of type 2 diabetes is obesity-induced insulin resistance in non-adipose tissues, combined with insufficient insulin secretion by pancreatic β-cells to overcome this resistance." (PMID 40362769, 2025). "Moreover, our study identifies a significant association between increased GDF-15 concentration and insulin resistance, as indicated by the homeostatic model assessment of insulin resistance (HOMA-IR) and serum insulin levels." (PMID 40722664, 2025). "The results demonstrated that maternal insulin resistance and hyperinsulinemia impair endocrine pancreas development and lead to metabolic disturbances in offspring, including higher postnatal glucose, insulin, leptin, glucagon, and GLP-1 levels, along with reduced β-cell area and proliferation." (PMID 41007299, 2025). "Enhanced insulin secretion from pancreatic beta cells may serve as a response to transiently increased insulin resistance, reflecting an adaptive capacity that protects against long-term glucose dysregulation." (PMID 40005307, 2025). "Therefore, mapping the intracellular pathway of GLUT4 and identifying the key insulin-regulated sites disrupted by insulin resistance is critical for understanding both normal physiology and disease." (PMID 40806697, 2025). "In this context, our results indicate that tirzepatide may restore insulin signaling and mitigate insulin resistance, at least in part, through the suppression of Il1b expression." (PMID 41019552, 2025). "On the other hand, low magnesium concentration may impair insulin secretion from pancreatic beta cells, as magnesium acts as a cofactor, and it may increase tissue insulin resistance." (PMID 40282004, 2025).